BDNF (brain derived neurotrophic factor)
Diseases named in the same sentence as BDNF in open-access papers (continued):
Sharing a sentence is not in itself a finding about the gene and the disease.
diabetes (continued). "There were no significant intergroup differences on changes in BDNF or diabetes risk factors." (PMID 30363954, 2018). "Therefore, the down-regulation of BDNF and its receptor TrkB in the diabetic colon found from the present study may through the same molecular pathway to promote the colon remodeling in diabetes." (PMID 29930382, 2018). "In addition, resveratrol may prevent diabetes by augmenting brain-derived neurotrophic factor (BDNF), when levels are low in T2DM, and may enhance production of the anti-inflammatory lipid, lipoxin A4." (PMID 28574454, 2017). "However, it is unclear whether BDNF/TrkB signaling plays a role in the potential effect of celecoxib on cognitive dysfunction in diabetes." (PMID 28466254, 2017). "Thus, future studies of BDNF-induced inflammatory regulation in diabetes are needed." (PMID 29062839, 2017). "In addition, EE housing avoided a decrease in BDNF levels induced by experimental diabetes." (PMID 26312758, 2015). "It was shown that serum and retinal levels of BDNF are significantly reduced at early stages of diabetes in rats, and BDNF protects retinal neurons from hyperglycemia in vitro, supporting that decreased BDNF levels may damage retinal cells early in the course of diabetes." (PMID 25004165, 2014). "However, our findings suggested that inhibition of PARP that attenuates diabetes-induced changes in the expression of BDNF, synaptophysin, GS, and caspase-3 could be mediated by attenuating ROS generation." (PMID 24347828, 2013). "Upstream regulator analysis highlighted altered neurotrophic signaling in diabetes, with enhanced NGF/TRKA and diminished BDNF/TRKB activity, potentially driven by target-derived cues." (PMID 40667173, 2025). "Additionally, this systematic review and meta-analysis assessed the effects of different exercise parameters on BDNF levels in middle-aged and elderly patients with type 2 diabetes, while also considering the influence of blood collection timing, different blood samples, and diabetes duration." (PMID 40933306, 2025). "Some diabetes medications, while improving cognitive dysfunction, also enhance synaptic dysfunction by upregulating synaptic proteins including PSD 95, brain‐derived neurotrophic factor (BDNF), SYP, and synapsin‐1 (SYN1) in DACD rodent models." (PMID 40296350, 2025). "Noteworthy, in STZ-induced diabetes in rodents, the inhibition of p-CREB activity and CREB-related expression of synapse protein in hippocampus as well as decreased BDNF activity were." (PMID 40381124, 2025). "Our findings demonstrate that both HIIE and semaglutide mitigate diabetes-induced neuronal damage, improving learning and memory in db/db mice via the AMPK/BDNF and PKA/BDNF pathways, respectively." (PMID 40426650, 2025). "Although previous studies have indicated that exercise can improve brain-derived neurotrophic factor (BDNF) levels in middle-aged and older adults with type 2 diabetes mellitus (T2DM), discrepancies remain among the findings." (PMID 40933306, 2025). "While exercise can increase BDNF levels in healthy individuals, for T2DM patients, adopting the same exercise regimen as healthy individuals may only alleviate metabolic abnormalities but may not be sufficient to overcome the neurodegnerative changes caused by long-term diabetes." (PMID 40933306, 2025). "In the present study, we investigated the effects of diabetes on the structural damage of the cerebellum and memory-related (SYP, BDNF, PAX7, and SYNCAM1) genes." (PMID 37970442, 2023). "Hesperidin also increased the expression of CREB, BDNF, PKA, and the synaptic proteins within the hippocampus and amygdala of rats with diabetes, thus restoring the equilibrium within the pathway involving PKA/CREB/BDNF." (PMID 38234970, 2023). "In the present study, we tried to investigate the effects of diabetes on the structural and functional damage of the cerebellum and memory-related genes, including SYP, BDNF, and PAX7 genes in the cerebellum." (PMID 37970442, 2023).
diabetes (continued). "The role of SYP, BDNF, and PAX7 in memory and the effect of diabetes on the reduction of these genes have been reported in several studies." (PMID 37970442, 2023). "IF mediates the Notch1 and BDNF/CREB signaling pathways to induce stem cell differentiation to mature neurons and improve diabetes-induced cognitive impairment." (PMID 36911497, 2023). "The aim of the current study is to review the latest documents on the effect of garlic on diabetes, VEGF, and BDNF and, finally, to review the existing studies on the effect of garlic on diabetic retinopathy." (PMID 36803536, 2023). "Diabetes increases the reactive oxygen species (ROS) level in cells and changes the expression of several genes, including SYP, BDNF, PAX7, and SYNCAM1, through the FOXO transcription factor." (PMID 37970442, 2023). "In addition, exercise training enhanced the neural BDNF/TrkB survival pathway and suppressed the neural apoptotic pathway in the diabetic cerebral cortex when considering a novel therapeutic strategy to prevent the development of apoptosis-related neurological diseases in diabetes mellitus." (PMID 35743182, 2022). "The increase in brain blood flow, neurotrophic factors such as brain-derived neurotrophic factor (BDNF), the reduction in cortisol, or the control of chronic diseases such as hypertension or diabetes can explain the cognitive improvements." (PMID 35955103, 2022). "BDNF serum levels were also found to be significantly reduced in T2DM patients and those with all kinds of diabetes-induced dementia, including VD and AD." (PMID 35682821, 2022). "Plasma levels of BDNF and LXA4 are low in Wistar rats that were induced to develop type 2 diabetes mellitus by STZ." (PMID 31823816, 2019). "Consistent with previous studies, the present study confirmed that diabetes induces the accumulation of Aβ1-42 in hippocampal CA1 and CA3 and reduces the expression of BDNF and MAP2." (PMID 31788335, 2019). "Analysis of neonatal risk factors for brain ID (baby weight Z-score, maternal BMI, maternal anemia, and maternal diabetes) as predictors of exosomal CNTN2 and BDNF levels were performed." (PMID 31623079, 2019). "In conclusion, STZ-induced diabetes up-regulated the expression of AGE, RAGE, TGF- β1 and TGF- β1 receptor and down-regulated the expression of BDNF and TrkB in different colon layers of rats mainly due to hyperglycemia." (PMID 29930382, 2018). "STZ-induced diabetes up-regulated the expression of AGE, RAGE, TGF- β1 and TGF- β1 receptors and down-regulated BDNF and TrkB in different layers of diabetic colon mainly due to hyperglycemia." (PMID 29930382, 2018). "Because BDNF/TrkB signaling pathway plays an important role in enhanced learning and memory, the restoration of protein expression of BDNF and p-TrkB by celecoxib may account for the protective role of COX-2 inhibition in diabetes-associated memory and learning deficit." (PMID 28466254, 2017). "Administration of edaravone significantly attenuated diabetes induced RGCs death, upregulation of ROS, ERK1/2 phosphorylation, and cleaved caspase-3 and downregulation of BDNF." (PMID 24897298, 2014). "In the present study, we investigated the correlations between the levels of BDNF and the levels of HMGB1 in the vitreous fluid and serum from patients with PDR and in the retinas of rats with diabetes." (PMID 23766563, 2013). "Western blot analysis was used to assess the effect of 1,5-isoquinolinediol on diabetes-induced alterations of p-ERK1/2, BDNF, synaptophysin, GS, cleaved caspase-3, and ROS." (PMID 24347828, 2013). "BDNF was significantly downregulated in the serum from patients with PDR and in the retinas of rats with diabetes, whereas HMGB1 was significantly upregulated." (PMID 23766563, 2013). "Administration of PARP inhibitor to diabetic rats significantly attenuated diabetes-induced increased expressions of PARP activation, ROS, p-ERK1/2, and cleaved caspase-3 and decreased BDNF, synaptophysin, and GS levels in the retinas." (PMID 24347828, 2013).
diabetes (continued). "Moreover, treatment with M. officinalis normalized hippocampal expression of brain‐derived neurotrophic factor (BDNF) and nitric oxide synthase (NOS) that were decreased by diabetes." (PMID 40927050, 2025). "It has been shown that plasma BDNF levels are lower in patients with T2DM than in those without diabetes and that plasma BDNF is inversely correlated with fasting blood glucose levels." (PMID 40002886, 2025). "The reduction in BDNF-impaired hippocampal long-term potentiation (LTP) is responsible for cognitive functions and insulin sensitivity, which may lead to diabetes." (PMID 39664526, 2024). "Although maternal diabetes did not alter hippocampal BDNF expression at P0, a marked downregulation of BDNF was observed in both hippocampal hemispheres of female and male offspring from the diabetic group at two weeks." (PMID 39518888, 2024). "In contrast, diabetes was found in 63.6% of the low BDNF group and 71.9% of the high BDNF group, which was not significantly different (p = 0.598)." (PMID 38397057, 2024). "However, a statistically significant difference was seen in sex ratio, duration of diabetes, post-prandial blood sugar, blood urea nitrogen (BUN), serum creatinine, and serum BDNF." (PMID 39712817, 2024). "This reviewsummarizes the potential roles of myokines such as myostatin, irisin,brain-derived neurotrophic factor, mitsugumin 53, meteorin-like, and apelin invarious CVD, including myocardial infarction, heart failure, atherosclerosis,hypertension, and diabetes." (PMID 39077334, 2024). "Diabetes can induce cognitive dysfunction by inhibiting the PI3K/AKT signaling pathway, inhibiting the activity of cAMP response element-binding protein (CREB), and downregulating the expression of the brain-derived neurotrophic factor (BDNF)." (PMID 36911497, 2023). "J147 can target mitochondrial adenosine triphosphate (ATP) synthase, increase levels of brain-derived neurotrophic factor (BDNF), improve memory, reduce infarct volume in embolic occlusion of the middle cerebral artery, and protect against diabetic mellitus-induced neuropathy." (PMID 37676534, 2023). "Therefore, we assessed the effects of diabetes on the expression of FOXO-regulated memory-related genes, including SYP, BDNF, and PAX7 genes in the cerebellum." (PMID 37970442, 2023). "In Dia + CM and Dia + INS groups, the mRNA expression level of BDNF was nonsignificantly higher than the diabetes group." (PMID 37081849, 2023). "Moreover, it inhibited diabetes-induced neuroinflammation by decreasing the inflammatory markers NfκB, TNF-α, IL-1β, and IL-6 and downregulating the BDNF/ERK/CREP pathway." (PMID 38105928, 2023). "In addition, the pre-diabetes elderly were found to have increased NGF, BDNF, and cathepsin B, and decreased Beta-Amyloid 1–42 and homocysteine." (PMID 35455914, 2022). "It has been found that in diabetic patients the plasma level of BDNF is significantly higher compared to patients with CKD but without diabetes." (PMID 36362520, 2022). "Multivariable logistic regression analysis was performed to investigate the risk factors of MCI in T2DM patients, including education levels (years), diabetes duration (years), the presence of CVD, serum HbA1c, HDL-C, creatinine, BDNF and apelin (OR = 0.304, 95%CI = 0.104–0.886; P = 0.029)." (PMID 35610700, 2022). "Second, the BDNF node was positively connected with diabetes in the high-FIM network but not in the low-FIM network." (PMID 36009129, 2022). "Apart from the elevated serum BDNF levels following AdipoRon treatment, BDNF levels in the hippocampal DG were increased, though diabetes did not alter BDNF levels in the dentate region (P = 0.743 vs. Control-Vehicle)." (PMID 34164760, 2021). "Second, this study compared the plasma levels of BDNF in patients with T2DM between groups with or without MCI in the different diabetes duration groups." (PMID 35111074, 2021).
diabetes (continued). "Our results indicated that, especially in the group with long-term diabetes, the serum BDNF level showed a negative correlation with FCP, 2hCP, and HOMA-IR, and this result is consistent with that of a study of Chinese patients with T2DM." (PMID 35111074, 2021). "After 12 weeks of aerobic exercise, when the experiment stopped, there was no significant increase in the resting BDNF levels in the group of patients with type 2 diabetes mellitus." (PMID 32012942, 2020). "Administration of vitamin D after induction of diabetes also did not change total hippocampal BDNF protein (2.79±1.35 ng/mg) (P-value >0.05)." (PMID 32405353, 2020). "Total hippocampal BDNF protein did not change after induction of diabetes (2.38±0.75 ng/mg), and differences were not significant compared to the healthy control group (3.14±0.91 ng/mg)." (PMID 32405353, 2020). "Current mechanistic study had found that diabetes inhibits cAMP-response element binding protein (CREB) activity and subsequently suppresses brain derived neurotrophic factor (BDNF) level via coordinately regulating PERK signaling and PI3K/AKT signaling in hippocampus, which were reversed by FGF1." (PMID 32460803, 2020). "BDNF resists NO-mediated glutamate metabolic cytotoxicity depending on its concentration, the latter comprising a possible neuroprotective role of BDNF in cases of FGR fetuses who present an activated brain-sparing effect, as well as macrosomic fetuses, especially in cases of maternal diabetes." (PMID 30622436, 2018). "Considering the toxic action of AGEs and protective roles of BDNF, it can be hypothesized that AGE-induced BDNF release is a biological defense system in the early phase of diabetes when the levels of AGEs are becoming higher." (PMID 28178976, 2017). "Exogenously applied neurotrophic factors, growth factors, and other biological molecules improved axonal regeneration and other neurological functions in animal models of diabetes; however, the translation of these molecules (e.g., NGF, BDNF, and VEGF) to humans has failed in clinical trials." (PMID 28203223, 2017). "In addition, the HMGB1 inhibitor GA attenuated diabetes-induced upregulation of HMGB1 and downregulation of BDNF in the retinas of rats." (PMID 23766563, 2013). "Administration of 1,5-isoquinolinediol did not affect the metabolic status of the diabetic rats, but it significantly attenuated diabetes-induced upregulation of PARP, ROS, ERK1/2 phosphorylation, and cleaved caspase-3 and downregulation of BDNF, synaptophysin, and GS." (PMID 24347828, 2013). "Quantification of BDNF levels in nondiabetic controls and the retinas of rats with diabetes was done with the use of ELISA." (PMID 23766563, 2013). "Diabetes and intravitreal administration of HMGB1 induced significant upregulation of the expression of HMGB1, TBARS, and cleaved caspase-3, whereas the expression of BDNF and synaptophysin was significantly downregulated in rat retinas." (PMID 23766563, 2013). "Additionally, BDNF enhances the activity of CREB, promoting the expression of anti-apoptotic and neuroprotective genes and enhancing synaptic plasticity, ensuring the preservation of functional neural circuits in the diabetic retina." (PMID 40003672, 2025). "A randomized clinical trial demonstrated that 1 g/d ethyl-eicosapentaenoic acid (E-EPA) could not significantly improve serum BDNF levels in patients with diabetes and major depression." (PMID 37012351, 2023). "The linear correlation analysis was conducted between BDNF and indicators of islet secretion in subjects with diabetes for more than 10 years, which presented a negative relationship [FCP (r = −0.260; p = 0.022); 2hCP (r = −251; p = 0.028); HOMA-IR (r = −0.312, p = 0.006)]." (PMID 35111074, 2021). "Moreover, in people with diabetic peripheral neuropathy, BDNF serum levels were lower in comparison with a group with diabetes without complications and a healthy control group." (PMID 32012942, 2020).
diabetes (continued). "Previously, we showed that BDNF is not only a neurotrophic factor but also protects pancreatic β cells against the cytotoxic action of alloxan, streptozotocin (STZ), doxorubicin (DX) and BP in vitro and thus, may prevent diabetes mellitus." (PMID 31823816, 2019). "Furthermore, plasma concentrations of BDNF and LXA4 were low in Wistar rats that developed STZ-induced type 2 diabetes implying that these molecules (BDNF and LXA4) have a role in the pathobiology of type 2 diabetes mellitus." (PMID 31823816, 2019). "Therefore, the up-regulation of BDNF and its signaling pathways in the PFC may be involved in the antidepressant effect of AST in diabetes." (PMID 32082151, 2019). "In order to investigate whether AGE, RAGE, TGF- β1 and their receptors play a role in the colon remodeling induced by diabetes, the expressions of AGE, RAGE, TGF- β1, TGF- β1 receptor, BDNF and TrkB were detected in the colon wall of streptozotocin (STZ)-induced rats." (PMID 29930382, 2018). "In addition, statistical analysis demonstrated that the polymorphisms of APOE, BDNF, GRIN2B, and HSP70-1 genes are not related with hypertension, diabetes, low blood pressure, and vascular disease." (PMID 25893192, 2015). "In the present cohort, plasma BDNF level was not significantly correlated with age, gender, BMI, smoking status, history of cardiovascular diseases, presence of dyslipidemia, hypertension or diabetes (data not shown)." (PMID 25153796, 2014). "After 4 weeks of diabetes, the retinas were harvested and the levels of reactive oxygen species (ROS) were determined fluorometrically and the expressions of PARP, phosporylated-ERK1/2, BDNF, synaptophysin, glutamine synthetase (GS), and caspase-3 were determined by Western blot analysis." (PMID 24347828, 2013). "Second, although diabetes medications were recorded, we did not account for other potential confounders such as diet, physical activity, stress levels, and additional pharmacological treatments that may have influenced BDNF levels." (PMID 40565316, 2025). "Second, exercise effects on BDNF levels in middle-aged and older adults with T2DM may be influenced by factors such as blood collection methods, sampling time, specifications of ELISA kits produced in different countries, age, duration of diabetes, and overall health status." (PMID 40933306, 2025). "Acute ischemic stroke (AIS) patients with diabetes mellitus (DM) have significantly lower brain-derived neurotrophic factor (BDNF) levels compared to nondiabetic patients." (PMID 41280373, 2025). "Furthermore, in a study involving 155 Chinese patients with diabetic retinopathy and/or nephropathy, serum BDNF levels were nearly half as low as among those who had no complications, thus suggesting BDNF as a potential independent indicator of diabetes complications." (PMID 35682821, 2022). "Here, we investigated whether systemic BHB affects the retinal levels of BDNF and local autophagy in diabetic mice with retinopathy; Methods: C57BL/6J mice were administered with intraperitoneal (i.p.)streptozotocin (STZ) (75 mg/kg) injection to develop diabetes." (PMID 36077579, 2022). "The unaltered BDNF mRNA levels in the injured diabetic GK tendons compared with the non-diabetic Wistar controls and the weak BDNF staining likely indicates that BDNF may not be a central regulatory molecule that is affected by diabetes, especially not at the two weeks healing time point." (PMID 28122008, 2017). "However, the diabetic patients in our study were not newly diagnosed; thus, the duration of diabetes alone could not explain the elevated level of serum BDNF." (PMID 25587547, 2014). "Thus, the findings of the present study on recognition memory could be related, at least in part, because the animal model of diabetes induced by alloxan did not alter BDNF levels." (PMID 22645603, 2012). "DMEM treatment did not affect the gene expression level of Bax, Bcl-2, BDNF, and TNF-ɑ compared to the diabetes group." (PMID 37081849, 2023).